RNU1-63P (RNA, U1 small nuclear 63, pseudogene)
Gene: Small nuclear RNA gene on chromosome 4 (67,429,591 to 67,429,754, reverse strand). Ensembl gene ENSG00000206629.
Homologues: Orthologues: chimpanzee U1 (99% identical), macaque U1 (92% identical), mouse Gm25818 (86% identical), rabbit U1 (85% identical). Paralogues in human: RNU1-1 (90% identical), RNU1-2 (90% identical), RNU1-27P (90% identical), RNU1-28P (90% identical), RNU1-3 (90% identical), RNU1-4 (90% identical), RNVU1-18 (90% identical), RNVU1-29 (90% identical), U1 (90% identical), RNU1-89P (89% identical), RNVU1-28 (89% identical), RNVU1-7 (89% identical), and 133 more.